ANXA1 (annexin A1)
Diseases named in the same sentence as ANXA1 in open-access papers (continued):
Sharing a sentence is not in itself a finding about the gene and the disease.
melanoma (continued). "Annexin A1 and annexin A2 could be other biomarkers that are necessary for the invasion of melanoma by signaling proliferation." (PMID 40305328, 2025). "Interestingly, we also observed that blood neutrophils from melanoma samples showed increased AnxA1 expression compared to nevus." (PMID 36766767, 2023). "Indeed, aggressive human melanoma cell lines express high amounts of AnxA1 related to cell invasiveness, as verified by impairing melanoma cell invasion when endogenous AnxA1 protein levels were reduced." (PMID 36766767, 2023). "Hence, we here depicted the role of AnxA1 secreted by neutrophils in lung melanoma mice and melanoma patients and unveiled the fact that AnxA1 derived from the blood or tumor-site neutrophils displays pro-tumor invasiveness during lung melanoma development." (PMID 36766767, 2023). "Hence, we addressed this issue, showing AnxA1 secreted by neutrophils contributes to the development of melanoma lung metastasis by promoting cancer invasiveness through FPR1/FPR2 pathways." (PMID 36766767, 2023). "Furthermore, the depletion of neutrophils reduced the levels of serum AnxA1, reinforcing the potential of AnxA1 as a melanoma biomarker." (PMID 36766767, 2023). "Conversely, the lung melanoma metastasis was composed of AnxA1+ tumor cells and immune cells." (PMID 36766767, 2023). "Herein, the reduction of neutrophils implied in the serum AnxA1 secretion decrease, which may impair melanoma cell invasion and, consequently, its dissemination." (PMID 36766767, 2023). "In addition, we observed a reduction of melanoma metastasis formation and serum levels of AnxA1 in neutrophil-depleted mice." (PMID 36766767, 2023). "Moreover, the treatment of the melanoma cells with the mimetic AnxA1 N-terminal peptide Ac2–26 stimulated the invasiveness by increasing MMP-2 expression, depending on FPR/MAPK/STAT3 activation pathways." (PMID 36766767, 2023). "AnxA1 expression was verified in four biopsy specimens (dysplastic nevus = 1; melanoma = 3)." (PMID 36766767, 2023). "Furthermore, a high expression of AnxA1 was found in circulating neutrophils (CD66b positive cells) from melanoma patients compared to nevus patients and the control, and serum AnxA1 levels were increased in patients with melanoma." (PMID 36766767, 2023). "Hence, this body of data drives a pivotal role of AnxA1 secreted by neutrophils in melanoma invasion via the FPRs axis." (PMID 36766767, 2023). "Once AnxA1 secreted by neutrophils displayed a role in melanoma metastasis, we further investigated whether depletion of these cells during the disease progression was able to alter the disease outcomes." (PMID 36766767, 2023). "Furthermore, Ly6G and AnxA1 double labeling or AnxA1 melanoma labeled cells showed that neutrophils expressed higher amounts of AnxA1 than melanoma cells." (PMID 36766767, 2023). "Indeed, lung metastasis induced by melanoma cells expressing AnxA1 is impaired in AnxA1-/- mice, addressing the fact that constitutive AnxA1 secreted by other mice cells are involved in the metastasis." (PMID 36766767, 2023). "Similarly, in a murine model of melanoma ANXA1 levels increased by 2.5-fold in B16B16 metastatic cells versus non-metastatic B16F10 cells." (PMID 29614751, 2018). "ANXA1 has not been extensively studied in melanoma, however one study implicated ANXA1 in melanoma metastasis." (PMID 25594008, 2014). "The notion that certain tumor entities, when exposed to the immune system, might exploit the immunosuppressive effect of annexin A1 is supported by the analysis of annexin A1 expression in some immunogenic tumor entities like melanoma." (PMID 23638088, 2013). "The tumors were grown in both annexin A1 null and wild type mice using B16 melanoma cells." (PMID 23077482, 2012). "Also, ANXA1 might present melanoma cell type specificity and according to our data together with PLEC were strongly down-regulated in highly pigmented MNT1 cells." (PMID 36776379, 2022).
melanoma (continued). "Other significantly reduced proteins include TRAIL, TGFR-2, ANXA1, SPARC, FURIN, GPNMB, and ERBB2, all of which play roles in melanoma progression, immune modulation, or resistance to targeted therapies." (PMID 40725203, 2025). "For this, murine melanoma B16F10 cells were applied, in which AnxA1 and its receptors (FPR1 and FPR2) were first characterized." (PMID 36766767, 2023). "On the basis of the concentration of AnxA1, NCM was divided into high and low AnxA1 content and employed to investigate the invasion of melanoma cells." (PMID 36766767, 2023). "Vimentin, nestin, annexin A1 (ANXA1) and fibronectin (FN1) were reported as predictive biomarkers for aggressive melanoma." (PMID 36776379, 2022). "A recent Phase I trial (NCT03784625) of melanoma-targeted radionuclide therapy showed that [131I]ICF01012 induces immunogenic tumor cell death, marked by a significant increase in cell surface Anxa1 and calreticulin." (PMID 33446132, 2021). "Which function mediated by ANXA1 in the context of MITF regulation in lung adenocarcinoma and melanoma progression, and how MITF regulates ANXA1 warrant further investigation." (PMID 33293474, 2020). "We examined expression of the three potential predictive biomarkers (ANXA1, CAV-1 and EphA2) in melanoma specimens by IHC." (PMID 25594008, 2014). "Moderate/strong expression of ANXA1, CAV-1 and EphA2 with co-expression of SRC kinase was found in 17 % of melanoma samples." (PMID 25594008, 2014). "SRC kinase has been shown to phosphorylate other members of the annexin family, in particular annexin 2 and we have previously shown that dasatinib treatment results in alterations in the phosphorylation status of ANXA1 and ANXA2 in WM-115 melanoma cells." (PMID 25594008, 2014). "Seventeen percent (19/112) of melanoma samples were positive for SRC kinase expression, combined with high expression of ANXA1, CAV-1 and EphA2." (PMID 25594008, 2014). "If SRC kinase staining is added to the panel, 19/113 (17 %) of the melanomas express detectable levels of SRC kinase and have moderate/strong expression of ANXA1, CAV-1 and EphA2." (PMID 25594008, 2014). "We examined expression of SRC kinase and the 3 potential predictive biomarkers, ANXA1, CAV-1 and EphA2, in a cohort of 125 melanoma specimens." (PMID 25594008, 2014). "Pearson correlation coefficient analysis was used to examine the relationship between mRNA and protein expression of ANXA1, CAV-1, CAV-2, EphA2, IGFBP2 and PTRF in the panel of melanoma cell lines." (PMID 25594008, 2014). "Moderate/strong expression of all three markers (ANXA1, CAV-1 and EphA2) was found in 21/113 (19 %) of the melanoma samples, 16/77 (21 %) of primary melanoma samples and 5/36 (14 %) of metastatic samples." (PMID 25594008, 2014). "We also used proteomic analysis and discovered differentially expressed melanoma exosomal proteins, including HAPLN1, GRP78, syntenin-1, annexin A1, and annexin A2." (PMID 23056502, 2012). "The function of circulating AnxA1+ neutrophils in melanoma is not yet known and deserves further investigation." (PMID 36766767, 2023). "Moreover, previous studies showed that AnxA1 stimulated MMP-2 activity by interaction with FPRs, increasing cell invasiveness and promoting the proliferation and migration of melanoma cells in vitro." (PMID 36766767, 2023). "Our findings show that AnxA1 secreted by neutrophils favors melanoma metastasis evolution via FPR pathways, addressing AnxA1 as a potential biomarker for the detection or progression of melanoma." (PMID 36766767, 2023). "Indeed, such melanoma cells co-cultured with neutrophils as incubated with NCM presented higher invasiveness, which was rescued if neutrophils were obtained from AnxA1-/- mice." (PMID 36766767, 2023). "Knockdown of ANXA1 in pancreatic ductal adenocarcinoma increases cell migration and invasion, but inhibits cell proliferation, which is similar to the phenotype at low levels of MITF in melanoma." (PMID 33293474, 2020).
melanoma (continued). "However, the genes ANXA1, PDGFC, VEGFC and LRRN3 were downregulated in CL1-0 shMITF-harboring cells, while they were upregulated in si-MITF melanoma 501MEL cells." (PMID 33293474, 2020). "We first found that ANXA1 expression was positively correlated with MITF expression in lung adenocarcinoma (Spearman’s correlation = 0.35, q < 0.001) but negatively correlated with MITF in melanoma (Spearman’s correlation = −0.34, q < 0.001)." (PMID 33293474, 2020). "Expression of ANXA1, CAV-1 and EphA2 were analysed in 124 melanoma samples by immunohistochemistry." (PMID 25594008, 2014). "Co-expression of SRC, ANXA1, CAV-1 and EphA2 was detected in 35/113 (31 %) of melanoma samples." (PMID 25594008, 2014). "Interestingly, elevated protein expression of ANXA1, CAV-1 and EphA2, determined by semi-quantitative immuno-blotting, correlated with dasatinib sensitivity in the melanoma cell lines." (PMID 25594008, 2014). "However, the intensity of AnxA1 labeling did not change according to melanoma cells migrating deeper or spreading into the dermis, suggesting that maintenance of constitutive AnxA1 expression is an effector molecule mediating the tumor progression." (PMID 36766767, 2023). "AnxA1 can be cleaved at different cells and tissues, such as in neutrophils, adipose tissue and melanomas; non-functional 33-kDa peptides released promote inflammation facilitating cell transmigration to inflamed areas, inducing adipogenesis and causing skin tumors to become more aggressive." (PMID 33519451, 2020). "In conclusion, our results suggest that IHC staining for ANXA1, CAV-1 and/or EphA2 may form the basis of a biomarker panel to select melanoma patients for a biomarker-driven clinical trial of dasatinib, to better define the potential clinical benefit of dasatinib in melanoma treatment." (PMID 25594008, 2014). "We found that ANXA1, FZD7 and PTGR1 were MITF direct targets in CL1-0 cells, but these genes were not regulated in melanoma 501MEL cells." (PMID 33293474, 2020). "We found that expression of ANXA1, CAV-1, CAV- 2, EphA2, IGFBP2 and PTRF mRNA did not correlate with response to dasatinib in the panel of 8 melanoma cell lines." (PMID 25594008, 2014).
prostate carcinoma (40 papers, 2007 to 2025). A carcinoma that arises from epithelial cells of the prostate gland. "Related experimental studies have found that ANXA1 is upregulated in various cancer tissues, including prostate cancer, and is associated with chemotherapy resistance." (PMID 37968699, 2023). "A decrease of Annexin A1 protein expression was observed in aggressive prostate cancer, and loss of Annexin A1 was associated with the tumorigenesis of prostate cancer." (PMID 32215176, 2020). "As with its pro-survival property, AnxA1 acts as a double-edged sword: secretion of either AnxA1 or Ac2-26 by tumor-associated fibroblasts induces the acquisition of stem-like features in prostate cancer cells, thus leading to a worse prognosis." (PMID 31336833, 2019). "In prostate cancer, reduced ANXA1 expression has been linked to prostate acinar morphogenesis due to increased IL-6 presence suggesting the importance of ANXA1 in mediating cytokine expression." (PMID 29614751, 2018). "Decreased expression of ANXA1 has been associated with prostate cancer and was postulated to enhance tumor aggressiveness via the induction of IL-6." (PMID 20021671, 2009). "Loss of function or expression of ANXA1 gene has been detected in multiple human cancers; as esophageal squamous cell carcinoma, gastric cancer, thyroid cancer, head and neck cancer, prostate cancer, endometrial carcinoma, and B-cell non-Hodgkin's lymphomas." (PMID 29091952, 2017). "However, ANXA1 overexpression is associated with metastasis and poor prognosis in multiple malignancies, including prostate cancers." (PMID 25481874, 2015). "Annexin A1 is a dual calcium and phospholipid binding protein which has been implicated in inflammation and numerous human cancers, including head and neck, pituitary and prostate cancers." (PMID 18637184, 2008). "Therefore, the loss of ANXA1 may be a useful marker for the development and progression of prostate cancer." (PMID 34512870, 2021). "Loss/aberrant expression pattern of ANXA1 in esophageal squamous cell carcinoma, prostate cancer, and endometrial carcinoma could be correlated with altered tumor behavior, e.g., dedifferentiation of tumor cells, increased invasiveness, and thus with tumor progression." (PMID 25038797, 2014). "The expression level of ANXA1 in B‐cell lymphoma, prostate cancer, and esophageal cancer was also significantly decreased." (PMID 40551992, 2025). "In vitro study results revealed that hampering the AR signaling ameliorates the migration of prostate cancer cells via the up-regulation of annexin A1 expression." (PMID 36969009, 2023). "In this study,we investigated the roles of RRM2 and the ANXA1 in regulating sensitivity to docetaxel therapy in prostate cancer." (PMID 37968699, 2023). "Our findings suggest that RRM2 regulates docetaxel resistance in prostate cancer by stabilizing ANXA1-mediated activation of the PI3K/AKT pathway." (PMID 37968699, 2023). "We evaluated the RRM2 expression, docetaxel resistance, and ANXA1 expression in prostate cancer cell lines and tumour xenografts models." (PMID 37968699, 2023). "This suggested that Annexin A1 downregulation mediated the suppression of EMT induced by HIF-1α knockdown in androgen-independent prostate cancer cells." (PMID 32215176, 2020). "We observed that Annexin A1 protein expression was increased by hypoxia in androgen-independent prostate cancer cells, which was inhibited by knockdown of both HIF-1α and TRPM7." (PMID 32215176, 2020). "Annexin A1 (ANXA1) is overexpressed in the invasive stages of prostate cancer and is involved in the acquisition and maintenance of stem-like/aggressive features in prostate cancer." (PMID 31303963, 2019). "Other studies in prostate cancer have also found a link between histone deacetylase inhibition, ANXA1 and apoptosis." (PMID 29614751, 2018). "Re-introduction of ANXA1 into prostate cancer cells induces a pro-apoptotic effect through blocking EGF-mediated proliferation and activation of p38 and JNK pathways." (PMID 29614751, 2018).
prostate carcinoma (continued). "In this study, we have characterized the role of annexin A1 (ANXA1) in the acquisition and maintenance of stem-like/aggressive features in prostate cancer (PCa) cells comparing zoledronic acid (ZA)-resistant DU145R80 with their parental DU145 cells." (PMID 26312765, 2015). "Elevated ANXA1 mRNA expression was found in dasatinib sensitive breast and ovarian cell lines, whilst EphA2 mRNA was elevated in breast, ovarian and prostate cancer cell lines." (PMID 25594008, 2014). "Evidence indicates that AnxA1 may also play an important role in tumor development and progression, with AnxA1 levels being up- and down-regulated in different cancers, e.g., the loss of AnxA1 expression in prostate cancer correlates with an early onset of tumorigenesis." (PMID 23230437, 2012). "Additionally, ANXA1 expression was notably elevated in docetaxel-resistant samples and prostate cancer tissues experiencing biochemical recurrence." (PMID 37968699, 2023). "Targeting RRM2 or ANXA1 may offer a promising therapeutic strategy to overcome docetaxel resistance in prostate cancer." (PMID 37968699, 2023). "The stabilization of ANXA1 by RRM2 may contribute to the development of resistance mechanisms in prostate cancer." (PMID 37968699, 2023). "However, the role of ANXA1 in regulating sensitivity to docetaxel therapy in prostate cancer is not well understood." (PMID 37968699, 2023). "In accordance with our result suggesting an increased expression upon oxidative stress induction, ANXA1 was also upregulated in prostate cancer cell line under hypoxia, a condition that may lead to oxidative stress." (PMID 36466095, 2022). "However, in prostatic cancer, ANXA1-exacerbated expression of this marker has been correlated with a high amount of cancer stem cells." (PMID 34073987, 2021). "Therefore, our findings reveal that Annexin A1 is a downstream molecular of TRPM7-HIF-1α signaling axis in prostate cancer under hypoxic conditions." (PMID 32215176, 2020). "It suggests the TRPM7-HIF-1α-Annexin A1 signaling pathway might serve as a potential drug target for the treatment of castrate-resistant prostate cancer." (PMID 32215176, 2020). "Thus, we determined if Annexin A1 expression was affected by HIF-1α in androgen-independent prostate cancer cells." (PMID 32215176, 2020). "Furthermore, this study showed that knockdown of Annexin A1 significantly reduced EMT in androgen-independent prostate cancer cells under hypoxic conditions." (PMID 32215176, 2020). "The role of Annexin A1 in prostate cancer cells is under controversy." (PMID 32215176, 2020). "Here, we proposed a hypothesis that TRPM7 might respond to hypoxia to regulate the degradation of HIF-1α, and thus to control its downstream target, Annexin A1, and subsequently to affect the hypoxia-induced aggressive ability of androgen-independent prostate cancer cells." (PMID 32215176, 2020). "Annexin A1 was found to be downregulated in MCF-7 and PC3 cancer cells, which is related to breast and prostate cancer development." (PMID 38249992, 2024). "Comprehensive Investigation: Our study comprehensively examined the role of the senescence-related gene RRM2, the ANXA1 protein, and the PI3K/AKT pathway in regulating sensitivity to docetaxel therapy in prostate cancer." (PMID 37968699, 2023). "The previous study revealed that Annexin A1 was upregulated by HIF-1α overexpression induced by hypoxia and played an essential role in prostate cancer." (PMID 32215176, 2020). "Next, we determined the effects of Annexin A1 on hypoxia-induced EMT and invasion of androgen-independent prostate cancer cells." (PMID 32215176, 2020). "In addition, We assessed the impact of RRM2 knockdown, ANXA1 over-expression, and PI3K/AKT pathway inhibition on the sensitivity of prostate cancer cells to docetaxel." (PMID 37968699, 2023).